GDPD1 (glycerophosphodiester phosphodiesterase domain containing 1)
Description:
Hydrolyzes lysoglycerophospholipids to produce lysophosphatidic acid (LPA) and the corresponding amines. Shows a preference for 1-O-alkyl-sn-glycero-3-phosphocholine (lyso-PAF), lysophosphatidylethanolamine (lyso-PE) and lysophosphatidylcholine (lyso-PC). May be involved in bioactive N-acylethanolamine biosynthesis from both N-acyl-lysoplasmenylethanolamin (N-acyl-lysoPlsEt) and N-acyl-lysophosphatidylethanolamin (N-acyl-lysoPE). In addition, hydrolyzes glycerophospho-N-acylethanolamine to N-acylethanolamine. Does not display glycerophosphodiester phosphodiesterase activity, since it cannot hydrolyze either glycerophosphoinositol or glycerophosphocholine (By similarity).
Synonyms: GDE4; FLJ37451
Tractability: Antibody: UniProt predicts a signal peptide or a membrane-spanning region. PROTAC: ubiquitination databases record sites on it; its protein half-life has been measured.
Gene: Protein-coding gene on chromosome 17 (59,220,467 to 59,275,970, forward strand). Ensembl gene ENSG00000153982.
Subcellular location: Cytoplasm; Membrane; Cytoplasm, perinuclear region; Endoplasmic reticulum
Pathways (Reactome):
Metabolism: Glycerophospholipid catabolism
Gene Ontology:
Molecular function: phosphatidylcholine lysophospholipase activity; phosphoric diester hydrolase activity
Biological process: N-acylethanolamine metabolic process; glycerophospholipid catabolic process; lipid metabolic process
Cellular component: cytoplasm; endoplasmic reticulum; membrane; endoplasmic reticulum membrane; perinuclear region of cytoplasm
Genetic constraint (gnomAD): Loss-of-function variants: 11 observed, 10.36 expected, observed/expected ratio (o/e) 1.06, 90% interval 0.67 to 1.7. The upper end of that interval is the gene's LOEUF score, 1.7, which puts it in group 6 of 6, group 1 being the genes least tolerant of losing a copy. Missense variants: 72 observed, 99.95 expected, observed/expected ratio (o/e) 0.72, 90% interval 0.6 to 0.88. Synonymous variants: 38 observed, 41.19 expected, observed/expected ratio (o/e) 0.92, 90% interval 0.71 to 1.21.
Homologues: Orthologues: chimpanzee GDPD1 (100% identical), macaque GDPD1 (99% identical), dog GDPD1 (96% identical), guinea pig GDPD1 (94% identical), rabbit GDPD1 (93% identical), mouse Gdpd1 (92% identical), rat Gdpd1 (90% identical), tropical clawed frog gdpd1 (74% identical), zebrafish gdpd1 (70% identical). Paralogues in human: GDPD3 (41% identical), GDE1 (21% identical), GDPD4 (21% identical), GDPD2 (18% identical), GDPD5 (18% identical).
Diseases named in the same sentence as GDPD1 in open-access papers:
GDPD1 is named in the same sentence as 5 diseases in open-access papers, as found by Europe PMC text mining. Sharing a sentence is not in itself a finding about the gene and the disease. The quoted sentences say what the papers report.
lung carcinoma (1 paper, 2022). "Thirty one down-regulated genes are known to be prognostic markers of lung cancer, 28 of which are of favorable prognosis, such as GDPD1, SLC46A3, CLIC6, LZTS3 or CCNO." (PMID 36544755, 2022).
retinal degeneration (1 paper, 2020). Degeneration of the retina. "Therefore, the potential convergent mechanism for retinal degeneration is transcriptional activation and expression of GDPD1 through juxtaposition of retinal TF binding sites within active compartments bounded by CTCF sites." (PMID 33022222, 2020).
GDPD1 also shares sentences with these, for which no sentence is quoted: tumor (2 papers); breast tumor (1); infection (1).